TNF (tumor necrosis factor)
Diseases named in the same sentence as TNF in open-access papers (continued):
Sharing a sentence is not in itself a finding about the gene and the disease.
prediabetes (continued). "In conclusion, low-grade inflammation measured with IP-10, TNF-α, RANTES, CD40L and VEGF was associated with prediabetes as defined by both OGTT and/or high HbA1c, with comparable levels of inflammation in subjects with prediabetes and T2D." (PMID 30143687, 2018). "TNF-α serum levels in our study in PCOS patients compared prediabetes were lower maybe related to different type of diseases, different measurement methods, different ethnic groups." (PMID 30134857, 2018). "Also, prediabetes with high insulin levels appears to increase TNF-α in patients." (PMID 31992349, 2020). "miR-192 was up-regulated in obese prediabetes and targeted PIK3R4, ACVR2B, and inflammatory mediators such as TNFα and IL-1β." (PMID 41400625, 2025). "In evaluating the mediator effect of TNF‐a, the indirect effect of T2DM on MoCA (X1b) was p = 0.668, with a test statistic of 0.428, and for the indirect effect of prediabetes on MoCA (X2b), it was p = 0.648, with a test statistic of 0.456." (PMID 39829127, 2025). "ROC curve analysis evaluated the predictive ability of four inflammatory markers-IL-18, TNF-α, IL-6, and NFATC4-for classifying prediabetes cases and controls." (PMID 40027364, 2024). "TNF-α and nesfatin-1 levels in T2DM were obviously different compared to prediabetes or the healthy; IL-6 and adiponectin levels in the healthy group were significantly changed in contrast to prediabetes or T2DM." (PMID 35311231, 2022). "For similar reasons, the TNF-α and IL-6 levels were significantly higher in the PICF of the prediabetes group." (PMID 36557041, 2022). "Adiponectin levels in the subgroups of prediabetes patients with HOMA-IR >2.8 were found to be strongly correlated with IL-6 (R = 0.6663, P = 0.005) or TNF-α (R = 0.7732, P < 0.001), but in the other three subgroups, there was no such correlation." (PMID 35311231, 2022). "The randomized controlled trails in obese and prediabetes subjects showed variable results such as reduced TC, TG, and LDL levels, and the inflammation markers hs-CRP, TNF, LPS, and MDA were also found to be reduced." (PMID 34359450, 2021). "That is, in the islet of prediabetes animal, β cells can regulate the autoimmune response by producing CXCL10, under the action of inflammatory factors such as IFN-γ and TNF-α." (PMID 35242125, 2021). "Similar analysis in Indians showed significantly higher levels of inflammatory biomarkers like high-sensitive C-reactive protein (hsCRP), IL1β, IL13, IL17A, IL6, TNFα, and IAP in individuals with prediabetes compared to normoglycemic individuals." (PMID 33658065, 2021). "The population of IFN-γ and TNF-α producing total CD4+ and CD8+ T cells are significantly increased in the PBMCs from the patients with prediabetes compared with normal subjects." (PMID 30867412, 2019). "In consistent with previous reports, IFN-γ and TNF-α production in total CD4+ and CD8+ T cells were increased in patients with prediabetes." (PMID 30867412, 2019). "Prediabetes is an aspect of PCOS, so TNF-α serum level results between case and control in our study is in line with this experiment." (PMID 30134857, 2018). "Moreover, immunohistochemical staining revealed that a higher concentration of TNF-α and IL-1β was present in the IMAT cells of prediabetes rats compared to the control group." (PMID 37899436, 2023). "For this purpose, we assessed the relationship between serum Vit D levels and acute phase reactants such as CRP, fibrinogen and ferritin and pro-inflammatory markers such as IL-1β, IL-6, IL-8, TNF-α, NF-κB and MAPK in newly diagnosed prediabetes and type 2 DM patients." (PMID 38136648, 2023). "In this case control study, we aimed to probe into the differences and connections of adiponectin, nesfatin-1, IL-6, and TNF-α levels in prediabetics, T2DM, and the normal participants in order to better understand the roles of these cytokines in the development of prediabetes and T2DM." (PMID 35311231, 2022).
prediabetes (continued). "Placebo had little impact on reducing serum TNF-α concentration (p = 0.3700), but FCE significantly inhibited the TNF-α concentration (p = 0.0001) of patients with prediabetes during the intervention." (PMID 35447934, 2022). "We expected to see worsened clinical and radiographic picture and elevated levels of IL-6 and TNF-α in the PICF of prediabetes as compared to the non-diabetic individuals." (PMID 36557041, 2022). "This demonstrated that after a high-fat intake, the triglyceride and TNF-α levels in patients with prediabetes increased more than those without diabetes, and the endothelial function of diabetic patients was also reduced significantly." (PMID 33921168, 2021). "Among Danes, individuals with prediabetes had significantly (Wilcoxon test, padj < 0.05) higher levels of interleukin 6 (IL6), tumor necrosis factor α (TNFα), lipopolysaccharide-binding protein (LBP), and intestinal alkaline phosphatase (IAP) compared to normoglycemic individuals." (PMID 33658065, 2021). "However, the increase in TNF-α levels in patients with prediabetes compared to controls was not statistically significant." (PMID 39408723, 2024). "On the other hand, considering the predictive character of this test, this screening method would facilitate the identification of 19% of subjects with prediabetes that would not respond due to high basal TNF-α values, under the conditions used for supplementation in this study." (PMID 35565903, 2022). "Subgroup analysis for CRP and TNF-α levels revealed a significant effect was pronounced in those with a definite diagnosis of T2DM and not in the patients with prediabetes." (PMID 41022286, 2025). "Significant differences in VCAM‐1 and TNF‐α levels were observed; however, these biomarkers did not mediate the effect of T2DM and prediabetes on cognitive functions." (PMID 39829127, 2025). "IL1-β, IL-6, IL-8, TNF-α, NF-κB, and MAPK were also significantly increased in the T2D and prediabetes groups compared to non-diabetic groups, indicating their role as pro-inflammatory factors." (PMID 39568808, 2024). "No significant variation of cytokines was observed between prediabetes and control group for IL-6, IL-10, IL-17A, IL-4, IL-8, IFN-γ, and TNF-α." (PMID 37457235, 2023). "This study revealed that the IL1-β, IL-6, IL-8, TNF-α, NF-κB and MAPK levels as pro-inflammatory markers and CRP, fibrinogen and ferritin as serum acute phase reactants were significantly increased in the prediabetes and T2DM groups compared to nondiabetes group." (PMID 38136648, 2023). "Materials and Methods: The clinical and radiographic parameters and the levels of IL-6 and TNF-α in the peri-implant crevicular fluid (PICF) of narrow diameter single (NDISCs) and splinted (NDISPs) crown implants were assessed both in non-diabetics and participants with prediabetes." (PMID 36557041, 2022).
Sjögren’s syndrome (69 papers, 2009 to 2025). "TNF levels in the blood and in lymphocytic infiltrates in salivary gland biopsies have been found to be increased in patients with Sjögren’s syndrome compared to controls, which was associated with salivary gland hypofunction caused by inflammation." (PMID 37894899, 2023). "In the current studies, addition of two other proinflammatory cytokines known to be associated with Sjogren’s syndrome pathophysiology, TNF-α and IFN-γ, seemed to potentiate (or synergize) the effects of IL-1β." (PMID 36147586, 2022). "The salivary gland hypofunction that occurs with Sjögren’s syndrome is associated with an increase in TNF-α." (PMID 35279651, 2022). "Additional genetic polymorphisms reported to be associated with risk for Sjögren’s syndrome include variants of interleukin 10 (IL-10), tumor necrosis factor (TNF), antigen peptide transporter 2 (TAP2), and 2′-5′-oligoadenylate synthetase 1 (OAS1)." (PMID 30626116, 2019). "As shown by Cay and his colleagues, polymorphism in the TNF-alpha gene promoter at position-1031 is associated with increased circulating levels of TNF-α, myeloperoxidase, and nitrotyrosine in primary Sjogren's syndrome." (PMID 23935646, 2013). "Our results indicate that an increased expression of TNF-αR and a higher sensitivity to TNF-α underlies the inflammatory/apoptotic profile displayed by acinar cells isolated from submandibular glands of NOD mice in the Sjögren's syndrome-like stage." (PMID 19356238, 2009). "An increased expression of TNF-αR and a higher sensitivity to TNF-α underlies the inflammatory/apoptotic profile displayed by acinar cells isolated from submandibular glands of NOD mice in the Sjögren's syndrome-like stage." (PMID 19356238, 2009). "According to a recent paper, even the responsiveness to targeted treatments is different in RA patients when associated with Sjögren’s syndrome, as follows: anti-tumor-necrosis factor (TNF)-alpha agents are less effective, whereas rituximab is more effective than in RA alone." (PMID 39061631, 2024). "Notably, Sjøgren’s Syndrome (SS) has been associated with overexpression of proinflammatory cytokines, including TNF-α, IL-7, IL-1β, IL-6, IL-10, IL-17, IL-18 and gamma-interferon (γ-IFN)." (PMID 29997338, 2018). "Increased activity of Th1 and Th17 cells has been demonstrated in both OCP and Sjögren’s syndrome, accompanied by elevated levels of IL-1β, IL-6, IL-17, TNF-α, and IFN-γ in periocular tissues." (PMID 41373875, 2025). "It has also been found that CEBPD is highly expressed in CD14(+) monocytes from patients with primary Sjogren's syndrome, and is involved in the TNF-α signaling pathway through NF-κB30." (PMID 38890389, 2024). "In the chronic inflammatory autoimmune disorder, Sjögren’s syndrome (SS), autoantibodies activate the TACE/TNF-a/NF-kB axis to exert their pathogenic effects." (PMID 35354403, 2022). "It is well known that TNF-α expression is elevated and plays important roles in salivary gland diseases such as Sjögren syndrome and IgG4-related sialadenitis." (PMID 32801121, 2020). "Such an induction of the gene expression of IL-8 and TNF-α was also evidenced in patients with Sjögren syndrome." (PMID 28640227, 2017). "The levels of TNF-α in patients with sicca syndrome (median 803 pg/mL, IQ range 116–1,498) were higher (P < 0.009) than that observed in patients without sicca syndrome (median 281 pg/mL, IQ range 0–946)." (PMID 26904697, 2016). "Detailed studies on the immune response in Sjögren’s syndrome patients treated with one of the inhibitors (etanercept) revealed an increase in the circulating levels of TNFα." (PMID 22759918, 2012). "The aim of this study was to assess the effect of a locally expressed tumor necrosis factor inhibitor on the salivary gland function and histopathology in an animal model of Sjögren's syndrome." (PMID 20003451, 2009).
Sjögren’s syndrome (continued). "Computational analyses have revealed that differentially expressed lncRNAs are involved in chemokine signaling pathways, the NF-κB signaling pathway, and the tumor necrosis factor (TNF) signaling pathway in labial salivary glands of Sjögren's syndrome patients." (PMID 34957168, 2021). "Long-term efficacy has also been reported for ustekinumab, not only against paradoxical forms of psoriasis induced by drug against TNF-α, but also against articular involvement in a patient affected by rheumatoid arthritis and in another affected by Sjögren’s syndrome." (PMID 28678161, 2017). "Thus, the data indicate that, at present, there is only limited use of biologics against primary Sjögren’s syndrome, even though the efficacy of TNF blockers remains in question." (PMID 28678161, 2017). "In contrast, TNFα inhibitors have been ineffective in the treatment of Sjögren's syndrome." (PMID 22759918, 2012). "In addition, CXCL13 production may be mediated by IL-1 in mice infected with IAV, by IL-22 in a mouse model of Sjögren’s syndrome and by TNF-α in the fat." (PMID 37047294, 2023). "Additionally, the pretreatment of polysaccharides at the dose of 1 μg/mL could inhibit the TNF-α-induced apoptosis of human salivary gland cell line A-253 cells, indicating its potential of protecting the salivary glands and ameliorating Sjogren's syndrome." (PMID 36160715, 2022). "These included a history for Sjögren syndrome (n = 4), a history of malignancy (n = 2), prior and concomitant therapy with disease-modifying anti-rheumatic drugs with established risk for PML (n = 9; the most common of which was MTX), and treatment with ≥ 2 prior TNF inhibitors (n = 4)." (PMID 29508305, 2018). "However the increased production of TNF-α and IFN-γ in this group of patients may contribute to the pathogenesis of sicca syndrome associated with HTLV-1." (PMID 26904697, 2016). "Tear proteomics has already identified cytokines and proteases—including IL-17, IL-6, TNF-α, and MMP-9—that correlate with disease severity in OCP, TAO, and Sjögren’s syndrome." (PMID 41373875, 2025). "Molecular profiling of tears has revealed elevated levels of IL-6, IL-17, TNF-α, and matrix metalloproteinase-9 (MMP-9) in patients with OCP, TAO, and Sjögren’s syndrome, correlating with disease severity." (PMID 41373875, 2025). "Some of the pro-inflammatory cytokines thought to play an important role in Sjogren’s syndrome pathophysiology are the interferons (IFN), IL-12, IL-18, TNF-α, IL-1β, IL-6 and B-cell activating factor (BAFF)." (PMID 36147586, 2022). "The study aimed to quantify certain cytokines involved in the pathomechanism of primary Sjögren syndrome (IL2, IL5, IL6, IL10, IL13, TNFα, IFNγ) and determine their common clinical correlation." (PMID 36143051, 2022). "The proinflammatory cytokines TNF-α and IFN-γ, are known to be elevated in chronically inflamed lacrimal glands as occurs in Sjogren’s syndrome." (PMID 36147586, 2022). "One study involved 58 patients with primary Sjögren's syndrome (pSS) with elevated levels of YKL-40, IL-6, and TNF-α." (PMID 36248435, 2022). "Our previous study pointed out that SS-1 inhibits Th1 (CD4+ IFN-γ+ and CD4+ TNF-α+ cells) and Th2 (CD4+ IL-4+ c cells) polarization of mouse spleen cells and T cell proliferation in Sjögren’s syndrome." (PMID 34200223, 2021). "An earlier report suggested that mRNA expression of Th1 and derived inflammatory cytokines IL-2, TNF-α, and INF-γ were also increased in the saliva of the patients with Sjögren’s syndrome." (PMID 32164227, 2020). "A number of OS- and NS-related hallmarks characterize Sjøgren's syndrome (SS) patients, including excess protein carbonyls and AGEs, 4-HNE, TNF-α, MPO, and 3-NT; moreover, excess 8-OHdG and hexanoyl-lysine were found in SS patients." (PMID 24876913, 2014).
Sjögren’s syndrome (continued). "These are due to extra-articular manifestation of RA itself, complication of Sjögren syndrome, and treatment with immunosuppressive agents including methotrexate (MTX) or tumor necrosis factor-α (TNF-α) blockers." (PMID 24839573, 2014). "Pro-inflammatory cytokines IL-1β, IL-6, IL-17 and TNF-α, as well as chemokines CXCL8, CXCL10, and CXCL13 are significantly elevated in the saliva of patients with Sjögren’s syndrome compared to healthy controls, and that their levels are correlated with the activity and severity of disease." (PMID 38714918, 2024). "Furthermore, interleukin levels such as IL-1a, IL-1b, IL-6, IL-8, TNF-a, and MMP-9 have been detected in Sjogren’s syndrome patients." (PMID 39408709, 2024). "Pro-inflammatory cytokine TNF-α expression is higher in the peripheral blood mononuclear cells (PBMCs) of patients with sicca syndrome than in those without sicca syndrome." (PMID 38047740, 2024). "It has been observed that in patients living with SS, the elevated expression of TNF-α can be found in both their serum and salivary glands, unlike the TNF-α levels encountered in patients that had sicca syndrome without having SS." (PMID 38398414, 2024). "An increased amount of HMGB1 has also been observed in the salivary glands of patients with Sjogren’s syndrome, and HMGB1 may act together with IL-1β and TNF-α in forming a feed-forward loop promoting inflammation." (PMID 28765610, 2017). "Moreover, those are present in Sicca syndrome; however, in this condition, the cluster presents low expression of CCL19, most likely reflecting the decreased level of inflammation and lower transcripts of TNFα and IFNγ in Sicca." (PMID 39747819, 2025). "In addition, expression of several genes known to be dysregulated in Sjögren's syndrome: CTSS, MHC-II, MMP9, Rab proteins (Rab3D, Rab27A, and Rab27B), IL12α, IFN-γ, TNF-α, and aquaporin 5 (Aq5), and the cholinergic muscarinic M3 receptor (M3R) were quantitatively measured using qPCR." (PMID 28348600, 2017). "Moreover, with a lower activity of NOS 1 in exocrine glands and higher serum levels of TNF-α, we recently reported an increased DNA fragmentation with increased Bax expression in isolated acinar cells from NOD submandibular glands at the Sjögren's syndrome-like period." (PMID 19356238, 2009). "Our findings suggest that expression of tumor necrosis factor inhibitors in the salivary gland can have a negative effect on salivary gland function and that other cytokines should be explored as points for therapeutic intervention in Sjögren's syndrome." (PMID 20003451, 2009). "More recently, the tumor necrosis factor (TNF)-α inhibitors infliximab and etanercept have been investigated for their efficacy and safety in patients with primary Sjögren’s syndrome and neither was found to be effective for improving disease outcomes." (PMID 27347394, 2016). "The production of TNF-α and IFN-γ was higher in the group with sicca syndrome (P < 0.05) than in HTLV-1 infected subjects without sicca syndrome." (PMID 26904697, 2016). "For example, high circulating levels of tumour necrosis factor-alpha (TNF-α) and transforming growth factor-beta (TGF-β) have been reported in patients with RA, but not in patients with Sjogren's syndrome." (PMID 19190628, 2009).